CCDC66 (coiled-coil domain containing 66)
Description:
Microtubule-binding protein required for ciliogenesis. May function in ciliogenesis by mediating the transport of proteins like BBS4 to the cilium, but also through the organization of the centriolar satellites. Required for the assembly of signaling-competent cilia with proper structure and length. Mediates this function in part by regulating transition zone assembly and basal body recruitment of the IFT-B complex. Cooperates with the ciliopathy proteins CSPP1 and CEP104 during cilium length regulation. Essential for cilium elongation, maintaining ciliary length and stability, and inhibiting disassembly (likely by stabilizing the axoneme) (By similarity). Also plays a role in ciliary Hedgehog pathway activation (By similarity). Plays two important roles during cell division. First, is required for mitotic progression via regulation of spindle assembly, organization and orientation, levels of spindle microtubules (MTs), kinetochore-fiber integrity, and chromosome alignment. Second, functions during cytokinesis in part by regulating assembly and organization of central spindle and midbody MTs. Plays a role in retina morphogenesis and/or homeostasis (By similarity).
Synonyms: DKFZp686C0433
Tractability: Antibody: its Gene Ontology location is reachable by antibodies, with high confidence. PROTAC: ubiquitination databases record sites on it.
Gene: Protein-coding gene on chromosome 3 (56,557,161 to 56,621,837, forward strand). Ensembl gene ENSG00000180376.
Subcellular location: Cytoplasm, cytoskeleton, microtubule organizing center, centrosome; Cytoplasm, cytoskeleton, microtubule organizing center, centrosome, centriolar satellite; Cell projection, cilium; Cytoplasm, cytoskeleton, cilium basal body; Cytoplasm, cytoskeleton, cilium axoneme; Photoreceptor inner segment; Cell projection, cilium, photoreceptor outer segment; Cytoplasm, cytoskeleton, spindle; Midbody
Subcellular location (Human Protein Atlas): Centriolar satellite; Perinuclear theca; Primary cilium; Cell Junctions; Cytosol; End piece; Midbody ring; Plasma membrane; Vesicles
Gene Ontology:
Molecular function: identical protein binding; microtubule binding; protein binding; protein homodimerization activity
Biological process: ciliary transition zone assembly; cilium assembly; establishment of mitotic spindle orientation; microtubule bundle formation; microtubule cytoskeleton organization involved in mitosis; microtubule nucleation; mitotic metaphase chromosome alignment; mitotic spindle assembly; mitotic spindle organization; regulation of cytokinesis; regulation of protein localization to cilium; cilium disassembly; positive regulation of smoothened signaling pathway; retina homeostasis; detection of light stimulus involved in visual perception
Cellular component: axoneme; centriolar satellite; centrosome; ciliary basal body; ciliary transition zone; cilium; microtubule; midbody; photoreceptor inner segment; spindle; photoreceptor outer segment
Genetic constraint (gnomAD): Loss-of-function variants: 92 observed, 96.43 expected, observed/expected ratio (o/e) 0.95, 90% interval 0.81 to 1.13. The upper end of that interval is the gene's LOEUF score, 1.13, which puts it in group 4 of 6, group 1 being the genes least tolerant of losing a copy. Missense variants: 889 observed, 880.92 expected, observed/expected ratio (o/e) 1.01, 90% interval 0.95 to 1.07. Synonymous variants: 307 observed, 298.2 expected, observed/expected ratio (o/e) 1.03, 90% interval 0.94 to 1.13.
Homologues: Orthologues: chimpanzee CCDC66 (99% identical), macaque CCDC66 (96% identical), pig CCDC66 (79% identical), dog CCDC66 (74% identical), guinea pig CCDC66 (70% identical), mouse Ccdc66 (69% identical), rat Ccdc66 (67% identical), rabbit CCDC66 (67% identical), tropical clawed frog ccdc66 (41% identical), Drosophila melanogaster CG13251 (14% identical).
Diseases named in the same sentence as CCDC66 in open-access papers:
CCDC66 is named in the same sentence as 28 diseases in open-access papers, as found by Europe PMC text mining. Sharing a sentence is not in itself a finding about the gene and the disease. The quoted sentences say what the papers report.
colon carcinoma (8 papers, 2018 to 2025). "In another study on colon cancer, knockdown of circ-CCDC66 also improved the radiosensitivity of colon cells by upregulating miR-338-3p expression, providing a potential therapeutic target for patients with radioresistant colon cancer." (PMID 36358938, 2022). "The circRNA CCDC66 promotes colon cancer growth and metastasis." (PMID 31623628, 2019). "Future studies using 3D cultures of human colon carcinoma Caco-2 cells or MCF10A mammary epithelial cells, which do not form cilia, will be necessary to differentiate between the ciliary and non-ciliary contributions of CCDC66 to epithelial cell organization." (PMID 40729374, 2025).
retinal degeneration (6 papers, 2019 to 2025). Degeneration of the retina. "CCDC66 is a microtubule-binding protein, and dysfunction of its gene has been reported to cause retinal degeneration in both canine and mouse models." (PMID 38979372, 2024). "The CCDC66 mutations in animal models have been associated with retinal degeneration, with electrophysiologic finding of reduced scotopic a wave and photopic b wave." (PMID 38548946, 2024). "CCDC66 has been implicated in several developmental disorders including retinal degeneration and Joubert syndrome." (PMID 35849559, 2022). "Understanding the mechanism underlying this compartmentalization is required to gain insight into regulation of its various functions and the cellular defects that lead to CCDC66-linked retinal degeneration." (PMID 31582766, 2019). "Importantly, the retinal degeneration mutation disrupts the centrosomal and ciliary localization of CCDC66 and its interactions." (PMID 31582766, 2019). "Co-immunoprecipitation experiments demonstrated that CCDC66 interacts with numerous proteins that function in ciliogenesis (i.e. CEP72, CEP290 and PCM1) and CEP290 has also been previously implicated in retinal degeneration in human ciliopathies and mouse models." (PMID 33273526, 2020).
ciliopathies (5 papers, 2020 to 2025). "Our findings provide important insights into the maintenance and disassembly of the cilium and suggest that defects in cilium homeostasis, signaling, and tissue architecture contribute to the pathogenesis of ciliopathies associated with CCDC66." (PMID 40729374, 2025). "Here, we characterized CCDC66, a microtubule-associated protein linked to ciliopathies, as an important regulator of cilium maintenance and disassembly in mouse epithelial cells." (PMID 40729374, 2025). "Here, we elucidated the nonciliary functions and molecular mechanism of action of the ciliopathy-linked protein CCDC66, which we previously characterized as a regulator of ciliogenesis in quiescent cells." (PMID 35849559, 2022). "CCDC66 variants have been associated with inherited retinal degenerations (RDs) including canine and murine ciliopathies." (PMID 33273526, 2020). "Here we reconstituted in vitro the individual and collective activities of the ciliary tip module proteins CEP104, CSPP1, TOGARAM1, ARMC9 and CCDC66, which interact with each other and with microtubules and, when mutated in humans, cause ciliopathies such as Joubert syndrome." (PMID 39856351, 2025). "This would enhance our understanding of CCDC66-linked ciliopathies and could inform new therapeutic approaches for these and related diseases." (PMID 40729374, 2025). "The ciliopathy-linked protein CCDC66 is only known for its ciliary functions." (PMID 35849559, 2022). "As genetic variants affecting the primary cilium can cause ciliopathies in which RD may be either the sole clinical manifestation or part of a syndrome, our findings further support a role for CCDC66 in retinal function and viability, potentially through its ciliary function." (PMID 33273526, 2020). "CCDC66 is a MAP crucial for the proper formation and function of various microtubule-based structures and is linked to ciliopathies that affect the eyes and brain." (PMID 40729374, 2025). "As both photoreceptors and olfactory sensory neurons that undergo degeneration are ciliated, Ccdc66−/− mice appear to represent a ciliopathy-like disease." (PMID 33273526, 2020). "Because animal models could not predict with sufficient certainty what will happen in humans, further study is needed to map CCDC66 in human ciliopathies, and to understand the prevalence, phenotype and pathogenesis of CCDC66-related disease." (PMID 38548946, 2024). "Although no variants in CCDC66 have been definitively mapped to human ciliopathies, CCDC66 variants have been associated with RD in dogs and mouse." (PMID 33273526, 2020). "For example, CCDC66 is required for proper spindle orientation, which is critical for specification of the site of the cleavage furrow and distribution of cell fate determinants to daughter cells during architecture and organization of tissues affected in ciliopathies." (PMID 35849559, 2022). "Collectively, our findings identify CCDC66 as a multifaceted regulator of the nucleation and organization of the diverse mitotic and cytokinetic microtubule arrays and provide new insight into nonciliary defects that underlie ciliopathies." (PMID 35849559, 2022).
colorectal cancer (4 papers, 2019 to 2025). A primary or metastatic malignant neoplasm that affects the colon or rectum. "Our previous study found that a novel oncogenic circRNA—consisting exon 8–10 of CCDC66—is aberrantly expressed in colorectal cancer (CRC) tissues and cells." (PMID 32187976, 2020).
Joubert syndrome (3 papers, 2022 to 2025). Joubert syndrome (JS) is characterized by congenital malformation of the brainstem and agenesis or hypoplasia of the cerebellar vermis leading to an abnormal respiratory pattern, nystagmus, hypotonia, ataxia, and delay in achieving motor milestones. "Moreover, the interactome contained components of the CCDC66-linked Joubert syndrome module, such as ARMC9, TOGARAM1, CEP104 and CSPP1, known for their roles in cilium length regulation." (PMID 40729374, 2025). "Recently, CCDC66 was identified as part of the Joubert syndrome interaction network consisting of other MAPs such as CSPP1, TOGARAM1, and CEP290." (PMID 35849559, 2022). "Moreover, CCDC66 is part of a ciliary tip module that includes other MAPs such as CEP104, CSPP1, TOGARAM1 and ARMC9, which are mutated in the Joubert syndrome." (PMID 40729374, 2025).
lung adenocarcinoma (3 papers, 2018 to 2022). A carcinoma that arises from the lung and is characterized by the presence of malignant glandular epithelial cells. "As the research reported that cirRNA CCDC66 was positively regulated by c-Met in lung adenocarcinoma cells." (PMID 31994979, 2020).
cervical cancer (2 papers, 2021 to 2025). A primary or metastatic malignant neoplasm involving the cervix. "In the current study, we aimed to demonstrate the role of circ-CCDC66 in cervical cancer progression." (PMID 33407514, 2021). "Our study revealed that the expression of circ-CCDC66 was upregulated in cervical cancer tumor tissues, and circ-CCDC66 mediated the proliferation, migration, and invasion abilities of cervical cancer cells." (PMID 33407514, 2021). "Firstly, we measured the expression of circ-CCDC66 in thirty-six pairs of cervical cancer human samples." (PMID 33407514, 2021). "Subsequently, we investigated the role of circ-CCDC66/miR-452-5p/REXO1 axis in cervical cancer cellular progression." (PMID 33407514, 2021). "By performing CCK-8 and transwell assays, it was found that circ-CCDC66 knockdown significantly suppressed cervical cancer cell proliferation, migration, and invasion abilities." (PMID 33407514, 2021). "The expression of circ-CCDC66 was upregulated in cervical cancer tumor tissues in comparison with normal tissues, and correlated with later tumor stage and larger tumor size." (PMID 33407514, 2021). "Here, knockdown of circ-CCDC66 was found to attenuate cervical cancer cell proliferation, migration and invasion abilities in vitro, and inhibit cervical cancer cell growth in vivo." (PMID 33407514, 2021). "Circ-CCDC66 knockdown significantly suppressed cervical cancer cell growth in vivo, the representative image of xenotransplantation tumors showed the inhibitory effect of circ-CCDC66." (PMID 33407514, 2021). "Collectively, our study demonstrated the role of circ-CCDC66/miR-452-5p/REXO1 pathway in cervical cancer progression." (PMID 33407514, 2021). "Subsequently, it was found that circ-CCDC66 was upregulated in cervical cancer cell lines compared with normal cervical cell line H8, especially in Hela and SiHa cells, and mainly located in cell cytoplasm." (PMID 33407514, 2021). "Our study found that circ-CCDC66 sponged to miR-452-5p and negatively regulated its expression in cervical cancer cells." (PMID 33407514, 2021). "Furthermore, overexpression of circ-CCDC66 in cervical cancer cells were couple with promotive phenomenon in cell proliferation, migration and invasion." (PMID 33407514, 2021). "Next, we assessed the biological functions of circ-CCDC66 in cervical cancer cells." (PMID 33407514, 2021). "Circ-CCDC66 regulated REXO1 expression to modulate cervical cancer progression via miR-452-5p." (PMID 33407514, 2021). "In this study, we aimed to investigate the role of circ-CCDC66 in cervical cancer progression." (PMID 33407514, 2021). "In this study, we revealed that circ-CCDC66 acted as an oncogene in cervical cancer progression." (PMID 33407514, 2021). "Firstly, circ-CCDC66 expression in cervical cancer human samples were assessed, our findings suggested that circ-CCDC66 was highly expressed in tumor tissues, and associated with later tumor stage and lager tumor size, indicated that circ-CCDC66 might be involved in cervical cancer progression." (PMID 33407514, 2021). "However, the role circ-CCDC66 in cervical cancer development is still uncovered." (PMID 33407514, 2021). "Our findings indicated that circ-CCDC66 might be involved in the progression of cervical cancer." (PMID 33407514, 2021). "It was found that circ-CCDC66 was an efficient molecular sponge for miR-452-5p, and miR-452-5p directly targeted to REXO1 in cervical cancer cells." (PMID 33407514, 2021). "In cervical cancer, circ-CCDC66, a molecular sponge of miR-452-5p, can upregulate REXO1 expression by blocking the action of miR-452-5p to promote cell proliferation, migration, invasion, and accelerate cervical cancer progression." (PMID 40181128, 2025).
cervical cancer (continued). "CCK-8 and Transwell assays showed that the inhibitory effects of downregulated circ-CCDC66 on Hela and SiHa cells were rescued by REXO1 overexpression, suggested that circ-CCDC66 regulated REXO1 expression to promote cervical cancer progression via sponging miR-452-3p." (PMID 33407514, 2021). "Our results demonstrated the role of circ-CCDC66/miR-452-5p/REXO1 axis in cervical cancer progression, we might provide novel therapeutic targets for cervical cancer clinical intervention." (PMID 33407514, 2021). "Moreover, our results demonstrated that circ-CCDC66 promoted cervical cancer progression via miR-452-5p/REXO1 axis, indicating that circ-CCDC66 might be a novel therapeutic target for cervical cancer." (PMID 33407514, 2021).
colon adenoma (1 paper, 2021). An adenoma that arises from the colon. "The decreased plasma levels circ-CCDC66 and circ-ABCC1 were found to be associated with precursor lesions of CRC, including colon adenomas and adenomatous polyps, and circ-CCDC66 and circ-STIL expressions could be effectively applied in detecting early- stage CRC." (PMID 33816529, 2021).
colorectal polyps (1 paper, 2025). "Through qPCR analysis of plasma samples from 50 CRC patients, 50 with colorectal polyps, and 50 healthy individuals, circ-CCDC66 emerged as a promising biomarker for CRC detection capable of identifying polyps among healthy individuals." (PMID 40181128, 2025). "Through clinical plasma sample verification, we found that circ-CCDC66 was more highly expressed in colorectal polyps and CRC than in healthy controls." (PMID 40181128, 2025). "This indicates that circ-CCDC66 could serve as a biomarker for detecting CRC and may even identify the presence of colorectal polyps in healthy individuals." (PMID 40181128, 2025).
intestinal polyp (1 paper, 2025). Discrete abnormal tissue masses that protrude into the lumen of the intestine. "This indicates that the detection of circ-CCDC66 effectively enhanced the diagnostic efficiency for colorectal diseases (including intestinal polyps and CRC)." (PMID 40181128, 2025). "Compared to the healthy control group, there was an increase in the expression of circ-CCDC66 in the plasma samples of the intestinal polyp group, and the expression was higher in CRC." (PMID 40181128, 2025).
lymph node metastasis (1 paper, 2025). "The results showed that the expression level of plasma circ-CCDC66 was significantly and positively correlated with lymph node metastasis, nerve invasion, tumor size, and TNM staging." (PMID 40181128, 2025). "Furthermore, in CRC, the expression level of circ-CCDC66 was significantly different in the plasma of patients with lymph node metastasis, nerve invasion, tumor diameter greater than 5 cm, and advanced stage (stage III-IV)." (PMID 40181128, 2025). "The results showed that the expression level of plasma circ-CCDC66 was not significantly correlated with the age and gender of patients but was significantly positively correlated with lymph node metastasis, nerve invasion, tumor size, and TNM staging." (PMID 40181128, 2025).
myopia (1 paper, 2025). "By using scRNA-seq, the results showed that CCDC66 was consistently expressed in the embryonic retinas of mice, and its mutations disrupt cell proliferation by affecting the mitotic process, which provides a plausible mechanism for high myopia onset." (PMID 40867565, 2025). "CCDC66, which has been identified to be related to retinal atrophy and degeneration, emerges as a candidate gene that may contribute to high myopia." (PMID 40867565, 2025).
nasopharyngeal carcinoma (1 paper, 2023). A carcinoma arising from the nasopharyngeal epithelium. "We hypothesized that CCDC66 may have a similar regulatory mechanism in nasopharyngeal carcinoma radiotherapy resistance." (PMID 36624463, 2023).
osteosarcoma (1 paper, 2022). A usually aggressive malignant bone-forming mesenchymal neoplasm, predominantly affecting adolescents and young adults. "In dividing cells, CCDC66 also localized to multiple MT-based structures including the spindle MTs in prometaphase and metaphase, the central spindle in anaphase, and the midbody in cytokinesis in human osteosarcoma (U2OS) cells." (PMID 35849559, 2022).
papillary thyroid carcinoma (1 paper, 2022). "CircRNA coiled-coil domain containing 66 (circ-CCDC66) has been reported to be involved in several cancers, but its biological function and underlying mechanism in papillary thyroid carcinoma (PTC) remain unclear." (PMID 35264065, 2022).
renal carcinoma (1 paper, 2020). A carcinoma arising from the epithelium of the renal parenchyma or the renal pelvis. "The results showed that cir-CCDC66 was upregulated in renal carcinoma cells than the normal kidney cells." (PMID 31994979, 2020). "As there were no previous reports on the expression of cir-CCDC66 in renal carcinoma, we carried out the qRT-PCR to identify the presence of cir-CCDC66 in renal carcinoma." (PMID 31994979, 2020).
retinal diseases (1 paper, 2020). "As CCDC66 variants have been previously implicated in retinal diseases, we believe that our newly identified CCDC66 variant is causative for EOPRA." (PMID 33273526, 2020).